NLRP3 (NLR family pyrin domain containing 3)
Diseases named in the same sentence as NLRP3 in open-access papers (continued):
Sharing a sentence is not in itself a finding about the gene and the disease.
liver fibrosis (continued). "We then determined the expression of NLRP3 inflammasome and liver fibrosis-associated markers, liver granuloma and ALT/AST." (PMID 30635040, 2019). "Together, these findings indicate that NLRP3 inflammasome and NF-κB are both implicated in liver fibrosis." (PMID 30635040, 2019). "Our results show that NLRP3 inflammasome in KCs and HSCs are both implicated in the progression of liver fibrosis in mice infected with S. japonicum." (PMID 30635040, 2019). "In particular, the NLRP3 inflammasome has been frequently implicated in the pathogenesis of chronic inflammatory liver diseases that causes liver fibrosis." (PMID 32038610, 2019). "Growing evidence has linked NLRP3 inflammasome-driven inflammation to tissue damage and liver fibrosis in conditions such as drug-induced liver injury, alcoholic steatohepatitis (ASH) and angiotensin II (Ang-II)." (PMID 30635040, 2019). "NLRP3 inflammasome has been reported to play an important role in inflammation-associated liver fibrosis and atherogenesis." (PMID 29416034, 2018). "It has thus been demonstrated that NLRP3 inflammasome activation is required for schistosomiasis-associated liver fibrosis development in mice." (PMID 28808303, 2017). "Our findings support a schistosomiasis-associated liver fibrosis model in which NLRP3 inflammasome activation in HSCs, then results in HSCs activation, collagen deposition and fibrosis." (PMID 28808303, 2017). "Therefore, it is important to investigate the role of NLRP3 on hepatic bile acid metabolism and gut microbiota to discover underlying treatment strategies for liver fibrosis." (PMID 40689656, 2025). "Excessive activation of NLRP3 inflammasomes in mice can lead to hepatocyte pyroptosis and cause severe liver inflammation and fibrosis, and pyroptosis products IL-1β and IL-18 regulate the activation of HSCs and promote liver fibrosis in vitro." (PMID 40667485, 2025). "Moreover, pretreatment with NLRP3 knockdown reversed the upregulation of proteins associated with the NLRP3 inflammasome and liver fibrosis induced by GCDCA in LPS-primed LX2 cells, and IL-1β secretion was also reduced." (PMID 38172440, 2024). "Similarly, caspase 1 and NLRP3 knockout mice are protected against hepatitis and associated liver fibrosis." (PMID 37818376, 2023). "At present, it is unknown what effect, if any, inhibition of the NLRP3 inflammasome might have on age‐associated liver fibrosis." (PMID 36999514, 2023). "NLRP3 inflammasome-dependent pyroptosis has been implicated in liver fibrosis progression." (PMID 36429008, 2022). "Our experimental results confirmed that the NLRP3 inflammasome was overexpressed and activated during the process of liver fibrosis, suggesting that the increased levels of NLRP3 inflammasome proteins were associated with liver injury, liver fibrosis and HSCs activation." (PMID 35694250, 2022). "Besides, NLRP3 inflammasomes expressed in KCs cause inflammatory cytokine production and fibrotic collagen formation in schistosomiasis-induced liver fibrosis (SSLF) and idiosyncratic liver injury-induced fibrosis." (PMID 35707547, 2022). "This study aimed to explore whether the effect of ursolic acid (UA) on liver fibrosis was associated with the NOX4/NLRP3 inflammasome pathways and intestinal bacteria." (PMID 34530693, 2021). "Moreover, HSC specific gain-of-function mutation of NLRP3 in mice results in early onset of liver fibrosis." (PMID 34685598, 2021). "The mechanism by which the NOX4/NLRP3 inflammasome pathway is involved in liver fibrosis may be associated with disordered intestinal bacteria." (PMID 34530693, 2021).
liver fibrosis (continued). "Negligible changes in Il1b transcript levels and comparable level of liver fibrosis in NLRC5-deficient livers suggest that NLRC5-dependent NLRP3 inflammasome activation plays little pathogenic role in liver fibrosis induced by chemically induced hepatocyte injury." (PMID 34712238, 2021). "A chemical compound, GS-444217, that specifically inhibit ASK1 (Apoptosis signal-regulating kinase 1), a protein kinase upstream of JNK and p38, has been reported to reduce liver fibrosis in a mouse model with a Nlrp3 (NLR family pyrin domain containing 3) loss-of-function mutation." (PMID 33019495, 2020). "Furthermore, NLRP3 inflammasome and liver fibrosis-associated markers were both increased in the primary KCs and HSCs isolated from infected mice." (PMID 30635040, 2019). "To better demonstrate which kind of cells originated from NLRP3 inflammasome implicated in hepatic fibrosis (particularly in KCs or HSCs in mice infected with S. japonicum), we examined the co-localization of NLRP3 with the KCs marker F4/80 or with the HSCs marker α-SMA in liver tissues." (PMID 30635040, 2019). "The present study demonstrates that the age‐dependent decline in SIRT1 is linked to NLRP3 signaling which leads to severe and persistent liver fibrosis during liver injury, even after cessation of injury, in an experimental model of hepatotoxin‐induced liver fibrosis." (PMID 36999514, 2023). "Thus, the NLRP3 inflammasome is associated with liver fibrosis to a great extent." (PMID 32733951, 2020). "Activation of the NOD‐like receptor signaling pathway, particularly the NLRP3 inflammasome, is a key mediator of alcohol‐induced hepatitis and liver fibrosis." (PMID 41583017, 2026). "To definitively exclude the regulatory role of the IL-1β–NLRP3 inflammatory axis in our liver fibrosis model, we administered an IL-1β–neutralizing Ab to CCl4-induced fibrotic mice." (PMID 41474968, 2026). "The differential liver bile acids, gut microbiota, and altered signaling pathways were examined to find out the role of NLRP3 in liver fibrosis." (PMID 40689656, 2025). "Growing evidence suggests that autophagy regulates the NLRP3 inflammasome signaling pathway during liver fibrosis." (PMID 41413484, 2025). "Gentiopicroside has been reported to inhibit the TLR4 and NLRP3 signaling pathways in macrophages, which brought the release of inflammatory factors, improvement of hepatocyte pyroptosis, and alleviation of the hepatic fibrosis." (PMID 40761743, 2025). "For instance, exosomes derived from bone marrow mesenchymal SCs mitigate liver fibrosis in cirrhosis rat models by inhibiting PCNA/NLRP3/caspase 1/GSDMD-mediated pyroptosis." (PMID 40667485, 2025). "In this context, genetic knockout of NLRP3 ameliorated aldosterone-induced hepatic fibrosis, while spironolactone treatment inhibited NLRP3 activation and significantly reduced liver damage in fibrosis mouse models." (PMID 40868048, 2025). "We propose that prolonged arsenic exposure induces hepatocyte pyroptosis through IL-17/NLRP3 signaling; this results in the release of pro-inflammatory cytokines and subsequent activation of HSCs, which promote the development of liver fibrosis." (PMID 40278603, 2025). "Loss of myeloid XBP1 impairs BNIP3‐mediated mitophagy and promotes macrophage cGAS/STING/NLRP3 activation through leakage of mtDNA into the cytosol, thereby exacerbating liver fibrosis." (PMID 40211890, 2025). "Our previous study revealed that GCDCA promotes liver fibrosis via the NLRP3 inflammasome pathway in mice and that GW4064 alleviated the fibrosis caused by GCDCA." (PMID 39982108, 2025). "Our previous study also demonstrated that the NLRP3 inflammasome signaling pathway plays an important role in the development and progression of liver fibrosis and that knockout of NLRP3 can alleviate liver fibrosis." (PMID 40689656, 2025). "The current study further explored the role of NLRP3 in BA metabolism and gut microbiota to understand the role of NLRP3 in liver fibrosis." (PMID 40689656, 2025).
liver fibrosis (continued). "“Matrix,” “macrophage polarization,” “nonalcoholic fatty liver disease,” “NLRP3 inflammasome,” and “target” represent the current research frontiers in macrophages and liver fibrosis and are now in the burst phase." (PMID 40406489, 2025). "We sought to explore the potential of Danshensu as a therapeutic agent for liver fibrosis by targeting the pyroptosis-inflammasome signaling pathway, providing a basis for developing effective and safer NLRP3 inflammasome inhibitors." (PMID 40225863, 2025). "Experimental evidence from murine hepatic fibrosis models demonstrates that NLRP3-mediated hepatic stellate cell activation promotes the development of liver fibrosis." (PMID 40830103, 2025). "Ursolic acid mitigates Kupffer cell pyroptosis in liver fibrosis by modulating the NOX2/NLRP3 inflammasome signaling pathway." (PMID 40667485, 2025). "The focus was on examining the role of Danshensu in reducing reactive oxygen species (ROS) production and inhibiting the activation of the NLRP3 inflammasome, which are key factors in liver fibrosis and inflammation." (PMID 40225863, 2025). "It was reported that GCDCA can promote liver fibrosis via the NOD-like receptor family pyrin domain containing 3 (NLRP3) inflammasome pathway in mice, and gut farnesoid X receptor activation alleviated the fibrosis caused by GCDCA in our previous study." (PMID 39982108, 2025). "While our study identifies NLRP3 as a key modulator of bile acid and microbiota in liver fibrosis, several limitations warrant consideration." (PMID 40689656, 2025). "For example, a study demonstrated that the inhibition of pyroptosis by targeting caspase-1 or NOD (nucleotide-binding and oligomerization domain)-like receptor (NLR) protein 3 (NLRP3) significantly inhibits liver fibrosis or cirrhosis." (PMID 40667485, 2025). "The current study provides compelling evidence that the combined administration of PFD and LIR enhances the regenerative response, normalizes Beclin-1 expression, and modulates the NLRP3 inflammasome pathway, thereby alleviating liver fibrosis (LF)." (PMID 41413484, 2025). "It has been reported that the development of liver fibrosis in mice can be reduced by blocking one of the three NLRP3 inflammasomes (caspase-1, ASC, or NLRP3)." (PMID 40367564, 2025). "Our previous study revealed that GCDCA promotes liver fibrosis via the NLRP3 inflammasome pathway in mice and that GW4064 alleviates the fibrosis caused by GCDCA." (PMID 39982108, 2025). "Our previous study indicated that CCl4 promoted liver fibrosis in mice, and knockout of NLRP3 alleviated fibrosis, and current research also indicated that NLRP3 deletion attenuated CCl4-induced hepatic fibrosis." (PMID 40689656, 2025). "MCC950 an inhibitor of NLRP3 inflammasome activation, downregulated IL-1β expression and significantly reduced hepatic fibrosis." (PMID 39995661, 2025). "Research has demonstrated that the activation of the NLRP3 inflammasome in mouse hepatocytes can induce both pyroptosis and liver fibrosis." (PMID 40406118, 2025). "The study found that individuals with liver fibrosis exhibited significantly higher serum aldosterone levels, along with increased hepatic expression of NLRP3, a key inflammasome involved in fibrogenic signaling pathways." (PMID 40868048, 2025). "We aimed to explore the potential of Danshensu as a therapeutic agent for liver fibrosis by targeting the pyroptosis-inflammasome signaling pathway, thereby providing a basis for developing effective and safer NLRP3 inflammasome inhibitors." (PMID 40225863, 2025). "Our previous study indicated that GCDCA induces liver fibrosis via the NLRP3 inflammasome pathway in mice and that GW4064 relieves the fibrosis caused by GCDCA." (PMID 39982108, 2025). "Chrysin activates AMPK phosphorylation in hepatic fibrosis and inhibits NLRP3 inflammasome activation, reducing inflammatory injury and pyroptosis." (PMID 39966334, 2025).
liver fibrosis (continued). "Chrysin’s ability to inhibit NLRP3 inflammasome activation further highlights its therapeutic potential, particularly in conditions like hepatic fibrosis and synovial inflammation." (PMID 39966334, 2025). "This study summarizes approaches that mitigate liver fibrosis/cirrhosis through the anti-pyroptosis pathway, including inhibitors targeting NLRP3, GSDMD, and caspases in the pyroptosis pathway, natural plant compounds and biomaterials (SCs and exosomes)." (PMID 40667485, 2025). "Next, we investigated the role of NLRP3 knockout in regulating gut microbiota alterations during CCl4-induced liver fibrosis." (PMID 40689656, 2025). "In the current study, a CCl4-induced liver fibrosis model and NLRP3−/− mice were established to investigate the effects of NLRP3 on hepatic bile acid metabolism and gut microbiota." (PMID 40689656, 2025). "For example, the KCs-derived NLRP3 inflammasome can promote the occurrence of liver fibrosis by activating the nuclear factor kappa-B (NF-κB) signal pathway in Schistosoma japonicum-infected mice." (PMID 39635524, 2024). "The expression of NLRP3, ASC, caspase-1p20, and GSDMD was reduced by Pip treatment, which resulted in the inhibition of NLRP3 activation in pyroptosis and led to improved liver fibrosis." (PMID 38547097, 2024). "For instance, the role of S1PR2 in promoting inflammation initiation and liver fibrosis development through the NLRP3 pathway has been demonstrated." (PMID 38250717, 2024). "Pearson's correlation analysis showed that post-MAFLD hepatic fibrosis positively correlated with low expression levels of IL-1β, low expression levels of NLRP3, and high NFS values." (PMID 39179677, 2024). "We identified the NLRP3/Cleaved Caspase-1/IL-1β signaling in the liver to evaluate the impact of MP-40 on hepatic fibrosis and to clarify the mechanism of action of MP-40 in treating hepatic fibrosis." (PMID 39372196, 2024). "Many studies have demonstrated that inhibiting the NOX2/NLRP3 signaling axis can reduce inflammatory damage and liver fibrosis." (PMID 38250717, 2024). "This was evidenced by reduced NLRP3 production in TAA-induced liver fibrosis models treated with HA-mExo-FA." (PMID 39591185, 2024). "In mice, activation of the NLRP3 inflammasome resulted in hepatocyte pyroptosis, hepatic inflammation, and liver fibrosis." (PMID 38195584, 2024). "Third, aldosterone can trigger a direct sequence of events leading to the activation of hepatic stellate cells (HSC) and eventually liver fibrosis, primarily by inducing the activation of the NLRP3 inflammasome." (PMID 39363897, 2024). "According to previous literature, the activation of S1PR2 was found to promote inflammation and liver fibrosis through the NLRP3 pathway, as well as modulate neutrophil exocytic reticulum." (PMID 38250717, 2024). "In hepatic fibrosis miR-21 negatively regulated a key transcription factor necessary for NLRP3 expression." (PMID 38306359, 2024). "STING activates NLRP3 inflammatory vesicles through an epigenetic mechanism, which mediates hepatocyte pyroptosis and hepatic inflammation in liver fibrosis." (PMID 39183465, 2024). "This modification facilitates specific interaction with CD44 receptors, enhancing the anti-liver fibrosis effects of FA by inhibiting NLRP3-mediated pyrotosis." (PMID 39591185, 2024). "Some studies have shown that autophagy and NLRP3 inflammasomes have a significant effect on the process of liver fibrosis." (PMID 38182564, 2024). "KCs can modulate the occurrence and progression of liver fibrosis by regulating NOD-like receptor protein 3 (NLRP3) inflammasome, PRR, transforming growth factor-β (TGF-β) signaling pathway, and platelet-derived growth factor (PDGF) signaling pathway." (PMID 39635524, 2024). "In particular, after 4 weeks of the CDAA diet, wild-type mice developed isolated hepatic steatosis, whereas NLRP3 knock-in mice exhibited severe liver inflammation with increased infiltration of activated macrophages and early signs of liver fibrosis." (PMID 38380334, 2024).
liver fibrosis (continued). "Knockdown of the lncRNA Lfar1 in liver macrophages alleviates liver fibrosis by inhibiting LPS/ATP and LPS/Nigericin-induced macrophage pyroptosis, a result of NLRP3 inflammasome activation." (PMID 38380334, 2024). "Currently, galectin is considered a potential target for the early treatment of many liver diseases as it directly activates NLRP3 inflammatory vesicles, which play a key role in liver fibrosis." (PMID 38994199, 2024). "Recent studies have been conducted to study the effect of Tβ4 on liver fibrosis, but analysis of its role in the macrophage-HSC connection associated with the NLRP3 inflammasome was insufficient." (PMID 36834849, 2023). "Even though these studies gave broad insight into the cell-specific role of pyroptosis in liver fibrosis and inflammation, comprehensive data for the cell-specific impact of NLRP3 on MASLD/MASH is still scarce." (PMID 37664463, 2023). "The mechanism of liver fibrosis/cirrhosis involve activation of NLRP3 inflammasome, leading to the destruction of hepatocytes and subsequent metabolic dysregulation in humans." (PMID 37520548, 2023). "In contrast, the level of hepatic fibrosis decreased in NLRP3 knockout mice infected with Schistosoma japonicum, suggesting that pyroptosis is involved in the hepatic fibrosis of schistosomiasis." (PMID 38086792, 2023). "One of our interesting findings is that inhibition of the NLRP3 inflammasome reverses established liver fibrosis in young mice after injury recovery and protects against age‐ and alcohol‐associated liver fibrosis." (PMID 36999514, 2023). "Pyroptosis and hepatic fibrosis were induced by activating NOD-like receptor family pyrin domain containing 3 (NLRP3) inflammasomes in primary hepatocytes from mice, and blocking caspase-1 and GSDMD inhibited pyroptosis and hepatic fibrosis." (PMID 38086792, 2023). "MCC950‐mediated inhibition of NLRP3 protects against liver fibrosis during aging, thereby offering a therapeutic avenue with fewer side effects in the elderly." (PMID 36999514, 2023). "Previous studies have demonstrated that NLRP3 activation contributes to renal fibrosis, hepatic fibrosis, and pulmonary fibrosis, and inhibition of NLRP3 activation reduces the degree of fibrosis." (PMID 38268894, 2023). "Together, these findings suggest that the NLRP3 inflammasome activation plays an important role in the progression of liver fibrosis–cirrhosis–hepatocellular carcinoma." (PMID 37370025, 2023). "In an aging mouse model of alcoholic liver fibrosis, NLRP3 inhibition by MCC950 ameliorates chronic‐plus‐binge alcohol feeding‐induced liver fibrosis in old mice." (PMID 36999514, 2023). "The effect of JT002 treatment on systemic and hepatic inflammation and hepatic fibrosis was evaluated in vivo using a murine Nlrp3 knock-in (KI) model of human Muckle Wells syndrome." (PMID 37598239, 2023). "Asp attenuated liver fibrosis and reduced collagen production by suppressing the NF-κB/NLRP3 signaling pathway via upregulating the expression of NS3TP1." (PMID 36983568, 2023). "WT animals showed isolated hepatic steatosis while inducible Nlrp3 knockin mice showed severe liver inflammation, with increased infiltration of activated macrophages and early signs of liver fibrosis." (PMID 37664463, 2023). "Liu and colleagues found that liver expression of GSDMD, NLRP3, caspase-1 and IL-1β increased in Schistosoma japonicum-infected mice, leading to exacerbation of hepatic fibrosis." (PMID 38086792, 2023). "Although further investigations are warranted to fully elucidate the synergistic effect of IL-1RA on liver fibrosis and the NLRP3-inflammasome mechanism, the results of this study establish the therapeutic potential of C-192 for the treatment of fibrosis." (PMID 38004466, 2023). "The activation of the NLRP3 inflammasome, on the one hand, produces IL-1β and IL-18, leading to liver fibrosis." (PMID 36900523, 2023).